RNU6-1148P (RNA, U6 small nuclear 1148, pseudogene)
Gene: Small nuclear RNA gene on chromosome 5 (138,069,355 to 138,069,458, reverse strand). Ensembl gene ENSG00000222924.
Homologues: Orthologues: chimpanzee U6 (100% identical), macaque U6 (95% identical), pig U6 (72% identical), guinea pig U6 (66% identical), rabbit U6 (66% identical). Paralogues in human: RNU6-940P (82% identical), RNU6-742P (80% identical), RNU6-812P (80% identical), RNU6-1089P (79% identical), RNU6-1145P (79% identical), RNU6-1316P (79% identical), RNU6-20P (79% identical), RNU6-393P (79% identical), RNU6-409P (79% identical), RNU6-776P (79% identical), RNU6-797P (79% identical), RNU6-961P (79% identical), and 1285 more.